TTK (TTK protein kinase)
Diseases named in the same sentence as TTK in open-access papers (continued):
Sharing a sentence is not in itself a finding about the gene and the disease.
cancer (continued). "This supports our point, TTK inhibits apoptosis through AKT-mTOR pathway, which in turn leads to worsening of cancer." (PMID 36849137, 2023). "We assessed the expression of TTK and TBK1 mRNAs using the METABRIC database, using the cBioPortal for Cancer Genomics, an open-access resource for multidimensional cancer genomics datasets analysis tool." (PMID 36494865, 2022). "TTK inhibitors BAY 1161909 and BAY 1217389 in combination with antimitotic cancer drugs achieve obvious enhancement effects over paclitaxel or TTK inhibitor monotreatment through abrogating SAC in a variety of xenograft models." (PMID 35850753, 2022). "TTK recruits several regulators of the SAC, including KNL1, MAD1, and BUB1 kinases into centromeres, and is an essential protein in cancer cells." (PMID 36494865, 2022). "These lines of evidence provided the basis for NSC77201 directly regulating activities of TTK, NEK2, and CDK1, which result in antitumor effects in multiple cancer types." (PMID 34072728, 2021). "Liver hepatocellular carcinoma patients who were with advanced cancer stages inclined to have the higher mRNA expression levels of CDK1, HMMR, PTTG1, and TTK." (PMID 34187556, 2021). "Then, we explored the TTK, C16orf54, PPAT, CD3EAP, SLCO2A1, ACAT1, and GAS2L3 genes in the CBioPortal for cancer genomics." (PMID 33402113, 2021). "The interactive analysis tool was applied to confirm the expression level of the eight DEGs (SPP1, TTK, MELK, FOXM1, LYN, ARRB2, COL6A3, and CCL21) in cancer and normal tissues." (PMID 33829064, 2021). "mRNA levels of TTK, NEK2, and CDK1 increased during the development of cancer from stage 1 to stage 4." (PMID 34072728, 2021). "These 8 genes (SPP1, TTK, MELK, FOXM1, LYN, ARRB2, COL6A3, and CCL21) were further validated in more numbers of cancer tissue samples by quantitative real-time PCR (qRT-PCR)." (PMID 33829064, 2021). "Thus, TTK may be a potential therapeutic target for cancers." (PMID 33282948, 2020). "We analysed cancer genomic datasets from the UCSC Xena website and found that TTK, CDC25A, and ESPL1 were highly expressed in EC tissues compared with normal tissues." (PMID 33282948, 2020). "Last, TTK, CDC25A, and ESPL1 showed higher expression in the late cancer stage and higher tumour grade." (PMID 33282948, 2020). "TTK protein kinase (TTK), also called Monopolar spindle 1 kinase (MPS1), is a HLA-A2402-restricted epitope peptide derived from cancer–testis antigens (CTA), and it is a previously unidentified member of the kinase family." (PMID 30656409, 2019). "The development of cancer-specific immunotherapy has been ongoing for many years, and several candidate targets such as MAGE-A, NY-ESO-1, LAGE-1, and TTK have entered early clinical trials." (PMID 30656409, 2019). "We found that TOP2A, TTK, CHEK1, and CENPA play critical roles in biological processes that are highly correlated with cancer, such as DNA topological structure, cell cycle progression, and mitosis, thereby suggesting their possible role in cancer development." (PMID 30886771, 2019). "We have identified a number of protein kinase genes which are upregulated commonly in cancers and are involved in the cell cycle regulation such as PLK1, TTK, BUB1, BUB1B, and PKMYT1." (PMID 28427185, 2017). "We identified consistently upregulated genes (such as E2F1, EZH2, FOXM1, MYBL2, PLK1, TTK, AURKA/B and BUB1) and consistently downregulated genes (such as SCARA5, MYOM1, NKAPL, PEG3, USP2, SLC5A7 and HMGCLL1) across various cancers." (PMID 28427185, 2017). "Most of these kinase genes have been shown to be overexpressed in various cancers such as PLK1, TTK, and AURKA/B." (PMID 28427185, 2017). "Fourteen genes that are essential to prevent EDR in cancer cells also are essential to prevent aneuploidy in mice [AURKA, BUB1B, BUB3, KIF11, MAD2L1, TPX2, TTK, SGOL1." (PMID 27144335, 2016). "For example the SDL interaction between PPP2R5D and TTK or PPP2R2D and BUB3 were identified across six different cancers." (PMID 27557495, 2016).
cancer (continued). "However, whether epigenetic alterations in cancer stimulate TTK expression is still unclear." (PMID 26418879, 2015). "We selected 5 peptide vaccines (TTK, URLC10, KOC1, VEGFR1 and VEGFR2) to overcome the immune-escape mechanisms and increase the therapeutic potential of the cancer vaccine." (PMID 24708624, 2014). "High levels of TTK mRNA have been found in BC, particularly in TNBC where it has been shown to protect cancer cells from aneuploidy." (PMID 23700430, 2013). "Current studies suggest that CCNB1, TTK, and CDC20 are overexpressed in various cancers." (PMID 40181976, 2025). "Targeting of either TTK or PLK1 has been clinically evaluated in cancer patients; however, dual inhibitors have not yet been pursued." (PMID 39184047, 2024). "This suggests that monitoring the levels of TTK, BUB1B, and BUB3 could potentially be useful in predicting the severity of carcinomas and guiding treatment decisions." (PMID 38987356, 2024). "The discovery of new members of oncogenic pathways, such as that of TTK and potentially PRKACA in the PI3K/AKT/mTOR pathway in this study, may help the identification of alternative targets for cancer treatment." (PMID 37352361, 2023). "There is evidence that CDC20, TTK, and CENPA were expressed and active in several types of cancer." (PMID 36213834, 2022). "Alternatively, the genes involved in genomic instability and growth of cancer cells (such as TTK and those identified here) can be targeted to initiate growth arrest in cancer cells without first increasing genomic instability or chaos." (PMID 34031527, 2021). "Our data suggest that the inhibitors of TTK and possibly other genes identified in this study have potential to inhibit/reduce growth and spontaneous as well as chemotherapy-induced genomic instability in EAC and possibly other cancers." (PMID 34031527, 2021). "Indeed, the chemical inhibitors of the kinetochore genes AURKB, TTK, and NDC80 have been proven effective in cancer therapy in preclinical studies." (PMID 33803928, 2021). "Problem 1 asked participants to predict molecules that bound the RETM955T-associated cancer pro-targets RET[M918T], BRAF, SRC, S6K, and did not bind the anti-targets MKNK1, TTK, ERK8, PDK1, and PAK3." (PMID 34520464, 2021). "Lastly, TTK, CDC25A, and ESPL1 showed higher expression in cancers with late stage and higher tumour grade, which indicates that they may be potential targets for improving EC patient prognosis." (PMID 33282948, 2020). "TTK, CDC25A, and ESPL1 showed higher expression in cancers with late stage and higher tumour grade." (PMID 33282948, 2020). "In addition, TTK, CDC25A, and ESPL1 showed higher expression in cancers with late stage and higher tumour grade, compared with early stage and lower tumour grade (P < 0.05)." (PMID 33282948, 2020). "The protein levels of CHEK1 and MCM10 were more significant in carcinomas than normal tissues and the differential expressions of KIF23 and TTK could be observed between primary lesions and liver metastases." (PMID 33134313, 2020). "Of note, 6 CTA genes CEP55, KIF2C, TTK, OIP5, CASC5, and NUF2 had higher expression levels in the higher-TMB subtype of at least 15 cancer types, while had higher expression levels in the lower-TMB subtype of at most 3 cancer types." (PMID 30634925, 2019). "The negative feedback loop might exist in TNBC cells and low level of TTK activates the B-Raf/ERK signaling, which contributes to the invasiveness of cancer cells and poor survival of patients." (PMID 27833085, 2016). "Indeed, we have examined several peptides derived from a variety of cancer-testis antigens that have the oncogenic activity, including KIF20A, DEPDC1, MPHOSPH1, URLC10(LY6K),TTK, KOC1(IMP3), CDCA1, RNF43, and TOMM34." (PMID 24237633, 2013). "Furthermore, many genes in cancer-related pathways were also over-expressed in high CIN samples including proliferation (ASPM, CKS1B, MCM gene family, TOP2A, TTK, TYMS) and cancer testis antigens (MAGE family)." (PMID 23840451, 2013).
cancer (continued). "Moreover, two CT genes, TDRD6 and TTK, were positively correlated with a number of immune cells, especially the CD4+/CD8+ T cells, implying strong host immune reactions to these two cancer antigens." (PMID 32728493, 2020). "Furthermore, inhibitors of TOP2A, TTK, and CHEK1, which are already used for treating certain cancers, could potentially be used in ACC treatment." (PMID 30886771, 2019). "In this study, we uncover a previously unknown mechanism by which TTK exerts a significant oncogenic effect by the upregulation of neurotensin (NTS) and dihydropyrimidinase-like 3 (DPYSL3), which promote cancer growth and cancer progression consequently tumor metastasis." (PMID 32121246, 2020). "Indeed, 30 out of 34 cancer-free tissues were completely negative for TTK." (PMID 27618777, 2016).
tumor (120 papers, 2008 to 2025). "CENPF, BUB1, BUB1B, KIF23 and TTK were identified as the key potential genes affecting hypoxia associated tumor stemness in this study." (PMID 33148251, 2020). "In the TTK gene mutation group, the tumor recurrence rate was about 18%, and the average survival period was 98 months." (PMID 32530571, 2020). "Inhibition of the spindle assembly checkpoint kinase TTK causes chromosome mis-segregation and tumor cell death." (PMID 28415765, 2017). "Univariate survival analysis revealed that LVI, increased tumor size, positive lymph nodes, advanced stage, specific chemotherapy regimen (Anthracycline+Taxanes (AT)-based regimen), and lower TTK expression were associated with shorter DFS." (PMID 27833085, 2016). "The expression of TTK in HCC tissues is associated with the Edmonson tumor grade, recurrence-free survival and overall survival." (PMID 26540467, 2015). "Finally, to ascertain if there was a prognostic association between TTK, radiosensitivity, and tumor stage in the TCGA HPV− and HPV+ HNSCC cohorts, we performed a multivariate analysis." (PMID 39392349, 2024). "Higher TTK mRNA expression was associated with tumor metastasis and advanced TNM stage." (PMID 38195567, 2024). "Importantly, inhibition of TTK counteracted the tumor-promoting effects caused by CWH43 downregulation." (PMID 37894942, 2023). "The current study also provides novel information about the signaling pathways associated with TTK overexpression and tumor aggressiveness in TNBC, including its interaction with TGF-β signaling and its regulation of the EMT regulators KLF5, miR-21, and miR-200s." (PMID 30206215, 2018). "Among these, key genes including TMEM106C, ECT2, PSMD2, STIL, and TTK showed significant upregulation in tumor tissues, and their high expression may be closely associated with abnormal activation of tumor stem cells, cell cycle regulation, and enhanced self-renewal capacity." (PMID 40766320, 2025). "To further investigate the potential anti‐tumor effects of targeting TTK in TCL, we used CFI‐402257 to selectively inhibit the activity of TTK." (PMID 39836493, 2025). "CFI‐402257 and NTRC 0066–0, inhibitors of TTK, show effective suppression of tumour growth in vitro and in vivo." (PMID 39775836, 2025). "Targeting TTK through gene knockdown exerts anti‐tumor effects in vitro and in vivo, including inhibiting the cell proliferation, inducing G2/M phase arrest, enhancing DNA damage and cell apoptosis." (PMID 39836493, 2025). "Targeting TTK pathways holds promise for BC treatment, as inhibiting TTK activity has shown efficacy in impairing tumour growth and enhancing chemotherapy sensitivity in pre‐clinical models." (PMID 39775836, 2025). "Comprehensive differential expression analysis between normal and tumor tissues revealed complex regulatory patterns of stem cell marker genes, with key genes such as TMEM106C, ECT2, PSMD2, STIL, and TTK showing significant upregulation in tumor tissues." (PMID 40766320, 2025). "In conclusion, monitoring the activities of these inhibitors not only on tumor cell growth but also on T-cell activity will be indispensable when TTK and ILK inhibitors are proposed for chemotherapy." (PMID 40274929, 2025). "To further assess the potential therapeutic role of TTK inhibition, we treated tumor-bearing mice with the TTK inhibitor CFI-402257." (PMID 40269198, 2025). "CFI‐402257, a specific inhibitor of TTK, is found to exhibit anti‐tumor effects and exerted synergistic efficacy with PI3K inhibitor, Duvelisib, in TCL." (PMID 39836493, 2025). "The protein and mRNA expression of TTK was significantly greater in tumor cell lines than in normal endometrial cell lines." (PMID 38195567, 2024). "Clinicopathological characteristics and ROC curve analysis of TTK expression revealed positive correlations between TTK mRNA expression and tumor metastasis and between TTK mRNA expression and high TNM stage." (PMID 38195567, 2024).
tumor (continued). "Research has found that TTK can accelerate the progression of tumors by promoting APC/C-CDC20-mediated mitosis in tumor cells." (PMID 39100078, 2024). "A preclinical study of a small-molecule TTK inhibitor identifies potent proimmunogenic activity reliant on the induction of tumor-intrinsic cytosolic DNA-sensing pathway." (PMID 38900577, 2024). "We analyzed the correlation between TTK expression and the infiltration of six tumor-infiltrating immune cells using the TIMER database." (PMID 38195567, 2024). "We discovered through immunofluorescence staining that the expression of TTK was reduced in tumor cells with knocked-down SAC3D1." (PMID 39100078, 2024). "Correlation analysis revealed a significant correlation of AURKA, AURKB, BUB1, HJURP, TOP2A, and TTK with tumor proliferation, G2M checkpoint, MYC targets, and DNA replication." (PMID 38726001, 2024). "TTK is a key spindle assembly checkpoint enzyme that regulates tumor cell proliferation across organisms." (PMID 38195567, 2024). "TTK mRNA expression and immune infiltration correlations were examined using the Tumor Immune Estimation Resource (TIMER) and the Tumor-Immune System Interaction Database (TISIDB)." (PMID 38195567, 2024). "This suggests that TTK knockdown can inhibit tumor growth and increase cisplatin cytotoxicity in vivo." (PMID 38601753, 2024). "TTK inhibitors exhibit heightened sensitivity toward tumor cells harboring CTNNB1 mutations, implicating CTNNB1 mutations as predictive genetic markers for patient response to TTK inhibitor therapy." (PMID 39100078, 2024). "Another asserted that increased TTK disrupts the spindle assembly checkpoint, fostering genome instability and tumor growth in colon cells." (PMID 37894942, 2023). "Through WGCNA analysis and GSEA enrichment analysis of transcriptome data from EC samples in TCGA, we found that TTK in EC samples mainly regulates the cell cycle by regulating mitotic checkpoints, thus promoting tumor progression." (PMID 36829176, 2023). "These analyses imply that TTK facilitates the division of genomically unstable tumor cells to sustain the proliferation and progression of EC cells." (PMID 36829176, 2023). "Another highlighted TTK’s unique regulatory role in tumor cell viability, mediated by its interaction with mitochondria." (PMID 37894942, 2023). "To determine TTK involvement in the tumor immune microenvironment, we assessed the immune cell infiltrates using the ESTIMATE algorithm." (PMID 37815894, 2023). "The mRNA expression of TTK was significantly higher in almost all tumor types in TCGA compared to normal samples." (PMID 36829176, 2023). "Our findings propose that the decreased expression of CWH43 amplifies TTK-mediated cell cycle activities, thus encouraging tumor growth." (PMID 37894942, 2023). "We have demonstrated that an AURKB/CASP-2 mechanism, regulated by the levels of BID, determines the fate of tumor cells after abrogation of the spindle assembly checkpoint by AURKB or TTK inhibitors." (PMID 37443114, 2023). "Mechanistically, TTK was found to regulate the proliferation and apoptosis of tumor cells through the Akt-mTOR pathway, where TTK knockdown inhibited its activation." (PMID 37770979, 2023). "Due to the vital role of immune cells in tumor progression and metastasis, we performed an immune cell infiltration analysis and found that TTK was significantly correlated with several immune cells." (PMID 37815894, 2023). "High expression levels of the TTK gene are closely related to tumor occurrence and poor prognosis, as confirmed by some studies." (PMID 35784389, 2022). "Immunohistochemical analysis of NSCLC specimens showed that the protein expression levels of USP9X and TTK were significantly increased in tumor tissues." (PMID 35784389, 2022).